MAFB (MAF bZIP transcription factor B)
Diseases named in the same sentence as MAFB in open-access papers (continued):
Sharing a sentence is not in itself a finding about the gene and the disease.
hyperglycaemia (3 papers, 2014 to 2020). "Taken together, Raptor is required for repressing MafB and other α-cell signature gene before the onset of hyperglycemia." (PMID 32439909, 2020). "Expression of several β-cell (Pdx-1, MafA, Nkx6.1 and Glut2) and α-cell (Arx, Pax6 and MafB) markers was examined to determine whether the molecular identity of islet cells was altered by exposure to chronic hyperglycaemia." (PMID 25145789, 2014).
insulinoma (3 papers, 2016 to 2023). "Further, c-MAF- and MAFB-mutant mice exhibited similar phenotypes to human patients, suggesting the need to create conditions conducive to insulinoma development." (PMID 37895232, 2023). "Other groups also observed increased cyclin B1 and D2 levels in MAFB-overexpressing insulinoma cells, and this was verified in our experiments." (PMID 27829226, 2016). "MafB downregulation reduced BrdU incorporation in the same insulinoma cell lines." (PMID 27829226, 2016). "Notably, differences exist between c-MAF- and MAFB-mutant mice and MAFA-mutant mice in terms of their proclivity to develop insulinoma, a typical disease in humans." (PMID 37895232, 2023).
leukemia (3 papers, 2014 to 2025). A malignant (clonal) hematologic disorder, involving hematopoietic stem cells and characterized by the presence of primitive or atypical myeloid or lymphoid cells in the bone marrow and the blood. "Our data prompt the idea that up-regulation of MAFB could be a potential mechanism by which MYB reduction affects the malignant cell phenotype in MLL-rearranged leukaemia." (PMID 37996430, 2023). "The finding of a strong inverse correlation between MYB and MAFB in MLL-driven leukaemia suggests that MAFB could serve as a new useful prognostic biomarker or predictive toward future MYB-targeted therapeutic strategies." (PMID 37996430, 2023). "Furthermore, MAFB itself could be regarded as an anti-leukaemia factor, which might be amenable to manipulation." (PMID 37996430, 2023). "Taken together, this suggests that MYB normally supports the leukaemia phenotype in MLL-rearranged AML by directly or indirectly limiting MAFB expression, with the additional possibility of suppression of MAFB protein activity, thereby limiting the ability of the cells to differentiate." (PMID 37996430, 2023). "Given the striking upregulation of MAFB in response to MYB suppression, we reasoned that ectopic expression of MAFB could phenocopy the consequences of MYB inhibition and, as such, could represent a novel therapeutic avenue for the treatment of MLL-rearranged leukaemias." (PMID 37996430, 2023). "Subsequent shRNA studies in KU812 leukemia cells and human erythroid progenitors generated from UCB-CD34+ cells supported a negative role of MAFB in γ-globin regulation." (PMID 25211130, 2014).
Nephropathy (3 papers, 2023 to 2025). A nonspecific term referring to disease or damage of the kidneys. "However, the relationship between MAFB variants and nephropathy in MCTO patients is unknown." (PMID 41235225, 2025). "Moreover, the reduced MAFB expression observed in one patient may indicate a potential role in the onset of nephropathy." (PMID 41235225, 2025). "Moreover, MCTO pathogenesis can be elucidated using an MAFB-mutant mouse model, which may contribute to the generation of novel treatments for MCTO and nephropathy." (PMID 37895232, 2023).
psoriasis (3 papers, 2022 to 2024). An autoimmune condition characterized by red, well-delineated plaques with silvery scales that are usually on the extensor surfaces and scalp. "PU.1-miR-148a-MAFB axis is a potential therapeutic pathway in psoriasis." (PMID 36248862, 2022). "miR-148a, after transcriptional activation by PU.1, also promotes monocyte-derived dendritic cell differentiation through the direct inhibition of MAF BZIP Transcription Factor B (MAFB), and this process results in immune imbalance and inflammatory response in psoriasis." (PMID 39519052, 2024).
Stroke (3 papers, 2019 to 2021). Sudden impairment of blood flow to a part of the brain due to occlusion or rupture of an artery to the brain. "In an experimental stroke model tamibarotene enhanced expression of both MafB and MSR1, and in turn reduced the infarct volume." (PMID 33670976, 2021). "Next, we examined the expression of V-maf musculoaponeurotic fibrosarcoma oncogene homolog B (MAFB) and MSR1 in the ipsilateral brain hemisphere, the function of which is to clear DAMPs (e.g., Prx1) after stroke." (PMID 34162400, 2021).
tuberculosis (3 papers, 2022 to 2026). A chronic, recurrent infection caused by the bacterium Mycobacterium tuberculosis. "v-Maf avian musculoaponeurotic fibrosarcoma oncogene homolog B (MAFB) is a candidate gene associated with early tuberculosis onset identified by a genome-wide association study." (PMID 41660610, 2026). "Our findings provide insights into a unique strategy for mycobacterial survival and the pivotal role of MafB as a biomarker for tuberculosis susceptibility." (PMID 40906796, 2025). "Meta-analyses of GWAS have reported increasing expression of MAFB in patients with active TB, and a recent study suggested an association between MAFB and M. tuberculosis infection in human monocyte cell lines." (PMID 40906796, 2025). "We also demonstrated that elevated MafB expression after M. tuberculosis infection reduced pro-inflammatory cytokine production and anti-tuberculosis activities, promoting mycobacterial survival and persistence." (PMID 40906796, 2025). "An increased expression of the transcription factor MAFB has been reported in patients with active tuberculosis; however, the significance of MafB in Mycobacterium tuberculosis infection remains poorly understood." (PMID 40906796, 2025). "MAFB, v-maf avian musculoaponeurotic fibrosarcoma oncogene homolog B, has been identified as a candidate gene for early tuberculosis (TB) onset in Thai and Japanese populations." (PMID 36406405, 2022). "Based on our current mouse studies, we conclude that elevated MAFB expression in patients with active TB likely promotes the persistence of M. tuberculosis, as observed in mice." (PMID 40906796, 2025). "Here, we investigated the genome-wide transcriptional profiles of MAFB-knockdown (KD) macrophages infected with Mycobacterium tuberculosis (Mtb) to highlight the potential role of MAFB in host immunity against TB." (PMID 36406405, 2022). "Having established that macrophages are the main source of MafB during M. tuberculosis infection, we next ascertained whether MafB-dependent cytokine restriction also occurs in experimental TB in mice." (PMID 40906796, 2025). "Although an increased expression of the transcription factor v-maf avian musculoaponeurotic fibrosarcoma oncogene homolog B (MAFB) has been reported in patients with active tuberculosis (TB), its potential role in Mycobacterium tuberculosis infection remains unknown." (PMID 40906796, 2025).
acute kidney injury (2 papers, 2019 to 2025). Sudden and sustained deterioration of the kidney function characterized by decreased glomerular filtration rate, increased serum creatinine or oliguria. "Although no direct link between NSAIDs and MAFB expression has been established, experimental models have indicated that COX/prostaglandin signaling modulates MAFB activity in macrophages during the recovery phase of acute kidney injury." (PMID 41235225, 2025).
adenoma (2 papers, 2014 to 2022). A neoplasm arising from the epithelium. "Further analysis indicated that the changes in methylation levels of the four iRFE MDGs, ADHFE1-Cluster1, CNRIP1-Cluster1, MAFB, and TNS4, occurred in adenoma tissues, while changes did not occur until stage IV in cell-free DNA." (PMID 36158666, 2022).
Autoimmunity (2 papers, 2017 to 2022). The occurrence of an immune reaction against the organism's own cells or tissues. "Moreover, MAFB in macrophages plays an essential role in resolving inflammation in ischemic conditions, efferocytosis preventing autoimmunity, and inhibiting macrophage apoptosis in atherogenic conditions, indicating that MAFB regulates the homeostatic function of macrophages." (PMID 36077342, 2022).
emphysema (2 papers, 2013 to 2024). "We previously demonstrated that MafB was upregulated in AMs in the lungs of mice with cigarette smoke-induced emphysema, suggesting a relationship between cigarette smoking and MafB expression." (PMID 24040127, 2013). "We previously demonstrated that the transcription factor MafB was upregulated in AMs in the lungs of mice with cigarette smoke-induced pulmonary emphysema." (PMID 24040127, 2013). "Studies have shown that MAFB participation in the pathophysiology of COPD affects the maturation and differentiation of macrophages and generates MMPs, ultimately leading to aggravated pulmonary emphysema and airflow restriction." (PMID 39091676, 2024).
gestational diabetes (2 papers, 2017 to 2021). Carbohydrate intolerance first diagnosed during pregnancy. "They identified MafB as one of the Prlr-signaling targets, and MafB deletion in maternal β-cells caused gestational diabetes as well." (PMID 33990661, 2021). "On the other hand, deletion of the MafB gene from β-cells, or deletion of the prolactin receptor which was shown to transcriptionally control MafB, resulted in a failure of adaptive expansion of β-cell mass during pregnancy, and the development of gestational diabetes." (PMID 28753672, 2017).
Hypercalcemia (2 papers, 2018 to 2023). An abnormally increased calcium concentration in the blood. "Her unexplained hypercalcemia after a regular dose of calcium and active vitamin D supported an important role of MafB in the negative regulation of RANKL-mediated osteoclast differentiation." (PMID 30305815, 2018). "For OS in NDMM patients, univariate analysis suggested that Age≥65, Albumin ≤ 35, Hypercalcemia, elevated LDH level, ISS III, R-ISS III, Gain 1q21, del 17p, MAF/IGH or MAFB/IGH, ASCT and VD/β-CTX at the time of MM diagnosis were risk factors." (PMID 37181039, 2023).
hypospadias (2 papers, 2025 to 2026). Hypospadias is the displacement of the urethral meatus on the ventrum of the penis. "We first detected the changes in gene expression of MAFB and associated genes of hypospadias foreskin tissues by RT-qPCR." (PMID 39569391, 2025). "For example, MAFB, FGF10, and FGFR2 are genes critical for urethral closure in both humans and mice, with mutations resulting in severe hypospadias." (PMID 41596366, 2026). "In this work, the specific role of MAFB in urethral epithelium was investigated, which advances our understanding of the contribution of heritable factors to hypospadias." (PMID 39569391, 2025). "We demonstrated the changes in the expression of MAFB, a key mediator of androgen action in the process of urethral masculinization, and other related genes in the prepuce of hypospadias patients." (PMID 39569391, 2025). "MAFB is essential for regulating male-type urethral differentiation, and especially, its variation can contribute to hypospadias in mice." (PMID 39569391, 2025). "Not only that, MAFB-KO male mice appeared abnormal fusion of the urethra, similar to the hypospadias phenotype." (PMID 39569391, 2025). "Our present work could enrich our cognition of the mechanism of the androgen-related gene MAFB in hypospadias formation." (PMID 39569391, 2025). "The role MAFB plays in hypospadias and the potential mechanism is intriguing." (PMID 39569391, 2025). "In the current study, we explored the effect of MAFB, CEBPA, and Wnt/β-catenin signaling in the pathogenesis of hypospadias." (PMID 39569391, 2025). "Moreover, MAFB and CEBPA expression were reduced in the prepuce tissues of hypospadias patients." (PMID 39569391, 2025).
Insulin resistance (2 papers, 2020 to 2023). Increased resistance towards insulin, that is, diminished effectiveness of insulin in reducing blood glucose levels. "As a result, we predict that these associated gene signatures will be induced even earlier than GAST itself upon pathologically induced loss of MafA or MAFB, which could be tested temporally in future studies in models of insulin resistance (i.e., following S961 or high-fat diet treatment)." (PMID 37606041, 2023). "Up-regulation of MAFB expression in human adipocytes has been correlated with adverse metabolic features and inflammation, which may lead to the development of insulin resistance." (PMID 32831068, 2020).
lung adenocarcinoma (2 papers, 2022 to 2023). A carcinoma that arises from the lung and is characterized by the presence of malignant glandular epithelial cells. "Moreover, all patients with smoking habits showed higher MAFB+ cell density and were at risk of poor OS and DFS, suggesting that MAFB could be a prognostic TAM marker in smoking patients with early-stage lung adenocarcinomas." (PMID 36077342, 2022). "In our previous report, tumor samples from patients with lung adenocarcinoma showed MAFB expression in locations comparable to CD68- and CD204-positive TAMs and were abundant in severe stages of cancer." (PMID 36077342, 2022). "Our results showed that MAFB+ cell density correlated with clinicopathological characteristics in patients with stage I, II, and III lung adenocarcinoma." (PMID 36077342, 2022). "Therefore, we analyzed whether the MAFB+ cell density was associated with survival rates of the patients with non-metastatic (Stage I to III) lung adenocarcinoma." (PMID 36077342, 2022). "Hence, our study suggests that MAFB shows a higher specificity to the macrophage/monocyte cell population than other cancer markers studied and could be used to identify patients with early stages of lung adenocarcinoma." (PMID 36077342, 2022). "However, the use of MAFB as a predictive marker for the survival of patients with non-metastatic lung adenocarcinoma remains unidentified." (PMID 36077342, 2022).
lung carcinoma (2 papers, 2017 to 2022). "Further, the lung tissue of 120 patients with lung cancer was immunostained using an anti-MAFB antibody, and the association between MAFB and cancer-related parameters was analyzed." (PMID 36077342, 2022). "In this study, the scRNA-seq analysis of patients with lung cancer showed MAFB expression in monocytes of tumor and advanced tumor tissue, while no other markers (CD204, CD68, CD206) were expressed." (PMID 36077342, 2022). "In this study, we evaluated the impact of silencing MafB in macrophages on the initiation and growth of lung cancer induced by urethane." (PMID 28900373, 2017). "This study was designed to investigate the role of MafB in a murine urethane-induced lung cancer model." (PMID 28900373, 2017). "Expecting the same for humans, MAFB may be a more specific TAM marker in lung cancer than other M2 macrophage markers." (PMID 36077342, 2022). "Furthermore, we have shown a significant upregulation of MAFB in human lung carcinomas (stage I and stage III)." (PMID 36077342, 2022). "CCR2 is the receptor for CCL2 which induces monocyte infiltration in tumors including lung cancer; therefore, MAFB may be a potential indicator for monocyte infiltration." (PMID 36077342, 2022). "It is assumed that MafB affects macrophage-mediated tumor immunity by altering their antigen presenting ability, which may affect the initiation and promotion of lung cancer in mouse models." (PMID 28900373, 2017). "However, the lack of expression of Mafb in AM, along with its cigarette smoke-induced increase in expression, led us to hypothesize that MAFB could be a potential TAM marker for lung cancer." (PMID 36077342, 2022). "Here, we analyzed the single-cell RNA sequence (scRNA-seq) data of human lung cancer previously reported to exhibit a lack of MAFB expression in AM but expressed specifically in another macrophage lineage." (PMID 36077342, 2022). "MafB silencing using dominant-negative MafB did not influence the initiation and growth of lung cancer in mice exposed to urethane." (PMID 28900373, 2017). "In conclusion, MafB silencing using DN-MafB does not influence the initiation and growth of lung cancer in mice exposed to urethane." (PMID 28900373, 2017). "The numbers and mean areas of lung cancer induced by urethane administration were not significantly different between wild-type and dominant-negative MafB transgenic mice." (PMID 28900373, 2017).
melanoma (2 papers, 2024). A malignant, usually aggressive tumor composed of atypical, neoplastic melanocytes. "On the other hand, three genes (MAFB, NUPR1, and SLC1A3), which were upregulated following combination therapy, showed low expression in the melanoma TCGA cohort." (PMID 38594618, 2024).
orofacial cleft (2 papers, 2016). A disorder of facial skeleton that is characterized by cleft lip and/or cleft palate that result in feeding, speech and hearing problems caused by failures during development. "The most significant of these, meeting the strict study-wide threshold for significance (i.e., p < 5 x 10−9), was the association of cranial base width at 20q12 410kb downstream of MAFB, a transcription factor previously implicated in orofacial clefts and facial characteristics in cleft families." (PMID 27560520, 2016).
ovarian carcinoma (2 papers, 2020 to 2025). A malignant neoplasm originating from the surface ovarian epithelium. "Taken together, these data elucidate a novel miR-10a-5p/RECQL4/MAFB axis that regulates the biological functions of ovarian cancer cells." (PMID 33014878, 2020). "Together, these data suggest that the MAFB is involved in RECQL4-mediated oncogenic behavior of ovarian cancer cells." (PMID 33014878, 2020). "MAFB became a point of focus, as its expression was found to be elevated in ovarian cancer in the TCGA cohort." (PMID 33014878, 2020). "This study suggested that MAFB silencing inhibited the proliferation and invasion of ovarian cancer cells." (PMID 33014878, 2020). "Transwell assays revealed that MAFB knockdown decreased the invasion ability of ovarian cancer cells." (PMID 33014878, 2020). "MAFB was also reported to promote the proliferation of ovarian cancer cells." (PMID 39569391, 2025). "MAFB mRNA expression positively correlated with RECQL4 expression in ovarian cancer tissues." (PMID 33014878, 2020). "Moreover, MAFB was upregulated in ovarian cancer tissues compared to FTs in the cohort from TCGA-GTEX." (PMID 33014878, 2020). "Moreover, upregulated RECQL4 promoted the growth and invasion and reduced olaparib/cisplatin sensitivity of ovarian cancer cells by increasing MAFB expression." (PMID 33014878, 2020).
periodontitis (2 papers, 2022 to 2024). An acute or chronic inflammatory process that affects the tissues that surround and support the teeth. "MAFB is suggested to be associated with the activation of SIGLEC5 expression and contribute to early-onset periodontitis." (PMID 39240858, 2024). "These experiments indicated that MAFB regulation is linked with activation of SIGLEC5 expression and with increased risk for early-onset periodontitis." (PMID 34852650, 2022).
rheumatoid arthritis (2 papers, 2015 to 2024). A chronic, systemic autoimmune disorder characterized by inflammation in the synovial membranes and articular surfaces. "MAFB (v-maf musculoaponeurotic fibrosarcoma oncogene homolog B) is a biomarker for rheumatoid arthritis." (PMID 26179165, 2015). "Previous studies have shown that the genetic knockdown of MAFB in chondrocytes using siRNA (MAFB Si chondrocytes) abrogated the increased matrix metalloproteinase (MMP3 and MMP13) gene expression in rheumatoid arthritis." (PMID 39054551, 2024).
Salmonella Infections (2 papers, 2013 to 2023). Infections with bacteria of the genus SALMONELLA. "MAFB was recently shown to be involved in the response of murine macrophages stimulated with either TLR agonists or subjected to Salmonella infection." (PMID 24339989, 2013).